PKM (pyruvate kinase M1/2)
Diseases named in the same sentence as PKM in open-access papers (continued):
Sharing a sentence is not in itself a finding about the gene and the disease.
malaria (2 papers, 2021 to 2022). Malaria is a serious and sometimes fatal disease caused by a parasite that commonly infects a certain type of mosquito which feeds on humans. "PKM was significantly increased during malaria in all monocyte subsets from Pv compared with HD." (PMID 34311577, 2021). "PKM is responsible for ATP production in substrate-level phosphorylation, thus supporting our hypothesis that during malaria, monocytes preferentially produce ATP via glycolysis." (PMID 34311577, 2021).
migraine (2 papers, 2022 to 2023). "We detected three energy metabolism-related enzymes (PKM, G6PD, and HK1) among the DEPs in the healthy controls and patients with migraine." (PMID 36248663, 2022).
preeclampsia (2 papers, 2024 to 2025). Preeclampsia is a hypertensive disorder of pregnancy that is characterized by new-onset hypertension with proteinuria presenting after 20 weeks of gestation, and depending on mild or severe forms may initially present with severe headache, visual disturbances, and hyperreflexia. "Then, immune microenvironment analysis turned out that M2 macrophages were reduced in preeclampsia women (p<0.0001) and were negatively correlated with the expression of PKM (r=-0.2, p<0.05), LEP (r=-0.4, p<0.0001), and HK2 (r=-0.3, p<0.001)." (PMID 38166707, 2024). "PKM, LEP, and HK2 could be promising biomarkers for preeclampsia, which might regulate the pathogenesis of preeclampsia via metabolism pathways and immune microenvironment." (PMID 38166707, 2024). "In summary, this research has identified PKM, LEP, and HK2 to be promising biomarkers for preeclampsia, which might regulate the pathogenesis of preeclampsia via targeting autophagy, metabolism and immune microenvironment." (PMID 38166707, 2024).
rhabdomyosarcoma (2 papers, 2018 to 2020). A rare aggressive malignant mesenchymal neoplasm arising from skeletal muscle. "Consistent with the PKM expression pattern of their tissue of origin, the majority of the examined rhabdomyosarcomas showed positive staining for PKM1 (32/48, 67%)." (PMID 29854399, 2018).
brain glioma (1 paper, 2021). A malignant glioma that involves the brain. "Thus, we propose PKM and TPI1 as suitable reference genes in gene expression studies in brain glioma biopsies." (PMID 34573317, 2021).
Burkitt lymphoma (1 paper, 2023). A rare form of malignant mature B-cell non-Hodgkin lymphoma. "Furthermore, we conducted immunohistochemical (IHC) staining to compare the protein expression of PKM and LDHA between the lymph node of Burkitt lymphoma (BL) and normal controls." (PMID 38099309, 2023).
colorectal adenoma (1 paper, 2015). An adenoma that arises from the colon or rectum. "In order to examine the expression profiles of PKM isoforms in the tumor samples from PKM2-dominant organ tissues, we investigated the expression levels of miRs-124, -133b, and PKM isoforms in 10 clinical colorectal adenoma and 10 cancer samples." (PMID 25721733, 2015).
dementia (1 paper, 2025). Loss of intellectual abilities interfering with an individual's social and occupational functions. "This upregulation of PKM by p-tau status was independent of dementia stage." (PMID 40667488, 2025).
familial Alzheimer disease (1 paper, 2025). A degenerative disease of the brain that causes gradual loss of memory, judgment, and the ability to function socially. "Furthermore, integration with data from familial Alzheimer's disease indicated ALDOA, ENO1, PKM and PGAM1 are all upregulated in the early to middle stages of disease onset." (PMID 40491829, 2025).
HCMV infection (1 paper, 2025). "Also down-regulated during HCMV infection is lactylation of gluconeogenesis proteins (cluster 3), whereas canonical glycolysis proteins show up-regulated lactylation sites (cluster 2), including PKM lactylation at K62." (PMID 39772686, 2025).
hearing loss (1 paper, 2022). "Other genes were related to BPD-associated outcomes such as retinopathy of prematurity (ROP, e.g., GBP3, FJX1, HIPK2) and hearing loss (e.g., GJB6, TMEM63B) and mitochondrial energy metabolism (e.g., TOMM7, SLC25A26, SLC25A33, PDK1, PKM, MDH1)." (PMID 35484630, 2022).
hypertrophic cardiomyopathy (1 paper, 2021). A condition in which the myocardium is hypertrophied without an obvious cause. "In addition, the expression of muscle fiber genes (MYH, MYL, and TNNI) and glycogen metabolism-related genes (PKM, PFKM, and PYGM) decreased, indicating that the massive accumulation of TTX has an impact on the hypertrophic cardiomyopathy pathway and cardiac muscle contraction pathway." (PMID 34822510, 2021).
mastitis (1 paper, 2022). Inflammation of breast tissue during lactation or postpartum due to an obstructed duct or infection. "When mastitis developed (T1/C1), GPI, TPI1, GAPDH, PGK1, PGAM1, ENO1, and PKM in the glycolysis/gluconeogenesis pathway were upregulated, which promoted pyruvate synthesis with large amounts of ATP production." (PMID 36335251, 2022).
myopia (1 paper, 2022). "Hence, as a cancer study revealed down-regulation PKM, this may indicate that atropine could diminish glycolysis during myopia progression." (PMID 35153787, 2022).
Renal cyst (1 paper, 2024). A fluid filled sac in the kidney. "In addition, enzymes for irreversible steps of glycolysis were upregulated in renal cysts, including hexokinase 1 and 2 (HK1, 1.7×; HK2, 6.2×), and pyruvate kinase (PKM, 1.6×)." (PMID 39000280, 2024).
sleep disorder (1 paper, 2018). A change from the patient's baseline sleeping pattern, in the hours slept and/or an alteration/dysfunction in the stages of sleep. "And PKM may represent an important novel target for metabolic and cardiovascular diseases associated with sleep disorders." (PMID 30235220, 2018). "Expression of four proteins including PKM, CLU, KNG1 and PFN1 were changed by CSD and these proteins can potentially serve as biomarkers for sleep disorders." (PMID 30235220, 2018).
soft tissue sarcoma (1 paper, 2018). A malignant neoplasm arising from muscle tissue, adipose tissue, blood vessels, fibrous tissue, or other supportive tissues excluding the bones. "To inform our study of PKM isoform requirements in soft tissue sarcomas (STS), we examined the expression patterns of PKM1 and PKM2 in normal adult skeletal muscle and STS tissue." (PMID 29854399, 2018).
cancer (1,261 papers, 2006 to 2026). A tumor composed of atypical neoplastic, often pleomorphic cells that invade other tissues. "The two isoforms encoded by the PKM gene are PKM1 and PKM2, with PKM2 being predominantly expressed in cancers." (PMID 40264038, 2025). "The splicing factorHNRNPA1, which contains two RNA recognition motifs (RRM1 and RRM2), has been linked to cancer progression by facilitating alternative splicing of PKM precursor mRNA exons." (PMID 37897508, 2024). "Pyruvate kinase isoenzyme type M2 (PKM2) encoded by PKM increases anabolic synthesis of macromolecules through the pentose phosphate pathway and consequently promotes proliferation and growth of cancer cells." (PMID 38347027, 2024). "The pathological isoform of PKM toward the cancer-associated PKM2 isoform causes metabolic and transcriptional changes." (PMID 37179826, 2023). "In cancer cells, serine has an important role associated with the activity of pyruvate kinase (PKM)." (PMID 37376060, 2023). "PKM1 and PKM2, two alternative splicing variants of the PKM gene, exhibited a switch in drug-resistant cancer cells, through the usage of mutually exclusive exons." (PMID 36810109, 2023). "Pathological isoform switching of the glycolytic enzyme pyruvate kinase M (PKM) toward the cancer-associated PKM2 isoform conferred metabolic and transcriptional changes in AD iNs." (PMID 35987203, 2022). "In this study, we focused on 14 different transcripts of PKM and systematically investigated the biological functions of each transcript as well as their association with the clinical outcomes in 25 different cancer types." (PMID 33478099, 2021). "The upregulation of some specific hnRNPs, hnRNP A1, hnRNP A2, and PTB, is involved in the splicing regulation of pyruvate kinase (PKM) and promotes the expression of cancer-associated PKM2 isoforms." (PMID 33923658, 2021). "PKM expression has been strongly associated with cancer survival, but the direction of the correlation is contradictory among different tissues of the human body." (PMID 32201876, 2021). "In this study, we investigated the associations of the alternatively spliced transcripts of PKM with cancer patients’ survival outcomes and explained the conflicts in previous studies." (PMID 33478099, 2021). "A splicing shift in the pyruvate kinase (PKM) gene in favor of PKM2 variant is also able to cause Gemcitabine and Cisplatin resistance in cancer." (PMID 34356101, 2021). "We focused on different transcripts of PKM and investigated the associations between their mRNA expression and the clinical survival of the patients in 25 different cancers." (PMID 33478099, 2021). "Pyruvate kinase M2 (PKM2) is a splice variant of the PKM gene that is expressed in some rapidly diving cells and overexpressed in many cancers, including PDAC, and has been described as a ‘master regulator’ of the Warburg effect." (PMID 32266066, 2020). "Here in this study, we present the first mechanistic evidence of curcumin causing the switch in the PKM splicing from cancer-specific PKM2-isoform to normal PKM1-isoform by inhibiting the DNMT3B in HNC cells." (PMID 31675998, 2019). "PKM2 is an alternatively spliced variant of the PKM gene that is highly expressed in various cancers and provides selective growth advantages for tumor formation over its counterpart PKM1." (PMID 31717694, 2019). "The deregulated alternative splicing of key glycolytic enzyme, Pyruvate Kinase muscle isoenzyme (PKM) is implicated in metabolic adaptation of cancer cells." (PMID 31675998, 2019). "In these tissues, PKM switching machinery causes an expression change from PKM1 to PKM2 during cancer development." (PMID 29695138, 2018). "Because of their impact on cancer progression, the molecular mechanisms underlying the choice between PKM exon 9 and 10 have been investigated by several groups leading to the identification of a group of relevant splicing factors." (PMID 30319972, 2018).
cancer (continued). "The muscle-specific pyruvate kinase M (PKM) isoform has also been implicated in metabolic reprogramming in certain cancers." (PMID 27358718, 2016). "Likewise, elevated SRSF3 expression drives preferential inclusion of exon 10 in PKM transcripts, promoting the cancer-associated PKM2 isoform that enhances glycolytic flux and tumor progression." (PMID 41465349, 2025). "Especially, the Warburg phenotype is closely related to the resistance of cancer cells to chemotherapy associated with increased aerobic glycolysis in which upregulation of key enzymes of glycolysis, including HK, PKM, PDH, and LDH, contributes to tumorigenesis and chemoresistance." (PMID 40089067, 2025). "Moreover, the RNA binding abilities of ENO1 and PKM have been linked to cancer progression and proliferation." (PMID 41175344, 2025). "For instance, a recent study quantified the mRNA level of PKM1 and PKM2 using RT-PCR and reported their association in cancer, but the primer they have used for RT-PCR could also bind to PKM-883 and PKM-609." (PMID 33478099, 2021). "It has been reported that the mRNA and protein expression of PKM is strongly associated with the survival of cancer patients, but the direction of the correlation was contradictory since both activation and inhibition of this enzyme have been suggested for effective treatment of the cancer patients." (PMID 33478099, 2021). "We observed that SRSF10 plays a crucial role in HNC tumorigenesis by affecting the pro-death, pro-survical splice variants of BCL2L1 (BCL2 Like 1: BCLx: Apoptosis Regulator) and the two splice variants of PKM (Pyruvate kinase M), PKM1 normal isoform to PKM2 cancer-specific isoform." (PMID 34616729, 2021). "However, the association of PKM expression and the survival outcome of patients with different cancers is controversial." (PMID 33478099, 2021). "In this study, we report that the intragenic DNA methylation‐mediated binding of BORIS (Brother of regulator of imprinted sites) at the alternative exon of Pyruvate Kinase (PKM) is associated with cancer‐specific splicing that promotes Warburg effect and breast cancer progression." (PMID 29460395, 2018). "The analysis of TCGA transcriptomic data and exon array data found that PKM gene intron 1 exhibits low methylation in multiple types of cancers." (PMID 40137167, 2025). "Pyruvate kinase M (PKM) splicing involves mutually exclusive exons and participates in coordinating the resistance of cancer cells towards chemotherapeutic agents." (PMID 40282556, 2025). "The upstream regulatory proteins can regulate abnormal expressions of splicing factors or change the interactions with PKM pre-mRNA, which eventually drives or affects metabolism programming in cancer cells." (PMID 38785973, 2024). "The complexity of RNA splicing and metabolic reprogramming in cancer biology is further highlighted by the regulation of glycolysis-related genes through the splicing isoforms of pyruvate kinase muscle (PKM), such as PKM1 and PKM213." (PMID 39285160, 2024). "Our findings clearly indicate that ZMYND11 plays a critical role in inhibiting HNRNPA1-mediated oncogenic activities, including PKM splicing and stress granule formation, both of which are crucial for cancer cell survival and proliferation." (PMID 39341825, 2024). "STAT5A signaling, CSPG4, MMP-1, MMP-3, MMP-8, MMP-9, and LUM are all involved in cancer cell migration, invasion, and metastasis, while PKM supports the growth and survival of cancer cells by favoring aerobic glycolysis." (PMID 39201614, 2024). "In our study, four glycolysis genes (ENO1, STMN1, PKM, and CDK1) have been previously reported to be associated with cancer progression and drug resistance." (PMID 38840205, 2024). "PKM is an isoenzyme of PYK, with M1 and M2 subtypes; PKM2 is typically expressed by cancer cells, and its upregulation can activate glycolysis and enhance malignancy." (PMID 39625960, 2024).
cancer (continued). "For instance, “glucosome” is an assembly of glycolytic enzymes including PFK, FBPase, PEPCK, and PKM, which is organized to regulate glucose flux in human cancer cells." (PMID 39622827, 2024). "HNRNPA1 has been shown to facilitate the excision of exon 9 from the PKM pre-mRNA, thereby selectively inducing the formation of the oncogenic PKM2 isoform, a key determinant of the Warburg effect that promotes aerobic glycolysis and cancer cell survival." (PMID 39341825, 2024). "RBMX prevents the formation of a specific cancer-promoting PKM isoform (Pyruvate Kinase M2 or PKM2), reducing cancer aggressiveness and glycolysis." (PMID 38539439, 2024). "The acetylated and phosphorylated hnRNPA1 increases its affinity with PKM pre-mRNA promoting PKM2 isoform generation and enhances cancer cell proliferation and invasion." (PMID 38785973, 2024). "A pivotal enzyme governing glucose metabolism in cancer cells is pyruvate kinase muscle isozyme (PKM)." (PMID 38680860, 2024). "GTPBP4 locates in the nucleolus and is a multi-functional protein involved in the biogenesis of 60 S ribosomal subunit, DNA mismatch repair system, PKM/PKM2-dependent glucose metabolism, cell cycle, and cancer." (PMID 38516932, 2024). "Of these, HSPA8, HSPA9, PKM, HNRNPA1, NPM1, ANXA2 are already reported to be associated with LN metastasis in GBC or other cancers." (PMID 37142981, 2023). "Simultaneously, several studies have revealed that cancer cells arise from normal cells by rewiring their metabolism via modulating the alternative pre-mRNA splicing of PKM to promote PKM2 expression." (PMID 36810109, 2023). "PKM has two isoforms, PKM1 and PKM2; PKM1 is expressed in differentiated tissues (i.e., brain and muscle), while PKM2 is expressed in cancer cells, embryonic cells, and in proliferating cells." (PMID 36959541, 2023). "PKM is one of the subtypes of pyruvate kinase, and its isozyme selection is related to the metabolic phenotype of cancer cells." (PMID 37124724, 2023). "SNHG3 acts as a sponge that inhibits miR-330 expression and increases PKM protein levels in cancer cells." (PMID 37204526, 2023). "We observed at the pan-cancer level that the expression pattern of FSTL3 and PKM varied greatly among different cancer types." (PMID 38044354, 2023). "The driver gene PKM is critical in tumor metabolism and has been found to be overexpressed in various cancers, promoting tumor cell proliferation and metastasis." (PMID 37737478, 2023). "PKM is a critical rate-limiting enzyme in glycolysis that regulates the generation of pyruvate, and as such it has been widely studied in cancer cells, a cell type with high metabolic activity." (PMID 37461556, 2023). "In terms of metabolism, the glucagon signaling pathway down-activates glycogenolysis and glycolysis by GYS and PKM, respectively, which are circuits that exhibit differential behaviors depending on the cancer type." (PMID 37834179, 2023). "Cancer cells exhibit a metabolic advantage by modulating alternative splicing of PKM to facilitate PKM2 expression." (PMID 36810109, 2023). "Relying on the representative KH3-4 domain, IGF2BPs can stabilize mRNAs; for example, overexpressed IGF2BP1 is shown to recognize the m6A sites in the 3' UTR of pyruvate kinase M1/2 (PKM2) via the KH3-4 domain to promote cancer progression." (PMID 37554271, 2023). "The dimeric PKM alternative isoform is also released into the circulation of cancer patients, promoting angiogenesis." (PMID 36672169, 2023). "hM1PYK (PKM1; expressed in the skeletal muscle, heart and brain) and hM2PYK (PKM2; expressed in all fetal tissues, adult smooth muscle and many cancers) are two gene products from the PKM gene that are generated via alternative splicing." (PMID 37171062, 2023). "PKM2 is an isoform of the PKM gene and plays a crucial role in the Warburg effect in cancer, and splice switching from PKM2 to PKM1 by ASOs restores the sensitivity of cancer cells to chemotherapy." (PMID 36271053, 2022).